APC (APC regulator of Wnt signaling pathway)
Diseases named in the same sentence as APC in open-access papers (continued):
Sharing a sentence is not in itself a finding about the gene and the disease.
multiple myeloma (9 papers, 2010 to 2022). "Treatment of human myeloma cell lines with proTAME, an APC/C inhibitor, resulted in an accumulation of APC/CCdc20 substrate cyclin B1 and an accumulation of cells in metaphase." (PMID 26716651, 2016). "The aim of this study is to elucidate the importance and therapeutic potential of APC/C and its co-activator Cdc20 in multiple myeloma (MM)." (PMID 26716651, 2016). "Apoptosis of TRAIL treated myeloma cells was assessed by flow cytometric analysis of APC-conjugated annexin V and 7-aminoactinomycin D (annexin V-APC/7 AAD) staining." (PMID 22615740, 2012). "Based on preclinical data reported on the APC/C inhibitor proTAME, it seems that targeting APC/C could indeed be an efficient strategy in myeloma treatment, especially in combination with standard of care agents." (PMID 29163849, 2017). "Mutations in APC do not occur with significant frequency in MM, and it remains unclear what specific mutations cooperate with Ras in myeloma development." (PMID 23825691, 2013). "However, evidence of APC involvement, such as a second somatic mutation of APC in multiple myeloma, needs to be found in order to rule out the possibility that the occurrence of the multiple myeloma was a coincidental unrelated event." (PMID 21078199, 2010). "The FISH probes used for the RPMI-8226 cells, a model of multiple myeloma, identifies the DLEU region of chromosome 13 covering the 13q14 gene and used a red (APC channel) fluorescent probe." (PMID 32102446, 2020).
pancreatic ductal adenocarcinoma (9 papers, 2018 to 2024). An infiltrating adenocarcinoma that arises from the epithelial cells of the pancreas. "The expression of APC is associated with poor survival in pancreatic ductal adenocarcinoma." (PMID 33801954, 2021). "One study on pancreatic ductal adenocarcinoma (PDAC) cell lines demonstrated that PIWIL1 acts as an oncoprotein by activating the APC/C E3 complex, enhancing PDAC metastasis through the targeted degradation of the cell adhesion-related protein, Pinin37." (PMID 39358554, 2024). "In the current study, we successfully knocked down APC in six pancreatic ductal adenocarcinoma cell lines; AsPC-1, BxPC-3, HPAF-II, Hs 766T, L3.6pl, and MIA PaCa-2." (PMID 31540078, 2019). "One very recent study conducted in human pancreatic ductal adenocarcinoma cell lines revealed that inhibition of extracellular signal-regulated kinase (ERK) led to dephosphorylation of Cdc20 and concomitant loss of APC/C target proteins securin and cyclin B (CCNB1 and CCNB2)." (PMID 39412391, 2024).
papillary thyroid carcinoma (9 papers, 2013 to 2026). "Sporadic APC mutations are reported to be associated with a rare cribriform-morular variant of papillary thyroid carcinoma in FAP, but they are also encountered in non-FAP patients." (PMID 31758407, 2020). "Although the siblings carrying APC mutation are follicular variant of papillary thyroid carcinoma in this study, we could not confirm whether they have adenomatous polyposis." (PMID 26530882, 2015).
retinoblastoma (9 papers, 2005 to 2022). A malignant tumor that originates in the nuclear layer of the retina.
triple-negative breast carcinoma (9 papers, 2017 to 2024). An invasive breast carcinoma which is negative for expression of estrogen receptor (ER), progesterone receptor (PR), and human epidermal growth factor receptor 2 (HER2). "Adenomatous Polyposis Coli (APC) is lost in approximately 70% of sporadic breast cancers, with an inclination towards triple negative breast cancer (TNBC)." (PMID 34370741, 2021). "In fact, lower expression CDC27 was found to be associated with poorer response to radiotherapy in squamous cell cervix carcinoma and Triple Negative Breast Cancer (TNBC) cells because of the important role of CDC27/APC in the mitotic regulatory pathway." (PMID 27974673, 2017). "APC/Ccdc20 inhibitor Apcin suppresses the metastasis in triple-negative breast cancer." (PMID 35301297, 2022).
tubular adenoma (9 papers, 2011 to 2026). A usually polypoid neoplasm arising from the glandular epithelium. "Colonoscopy revealed multiple polyps (>100), including tubulovillous adenoma and tubular adenomas, along with the APC mutation identified by germline genetic test." (PMID 40491286, 2026). "APC:c.1408+743_1408+745delinsACG located in intron 13 was detected in a patient with colon polyposis (38 tubular adenomas), which are associated with APC pathogenic variants." (PMID 35806449, 2022). "Within this family, the second hit of APC gene was detected in 3 out of 4 villous adenomas, 2 out of 3 tubular adenomas, and 3 out of 5 carcinomas." (PMID 39021676, 2024). "It was interesting that we identified the somatic mutation APC p.R1450* present in the villous adenoma of FAP07, tubular adenoma of FAP08, and villous adenoma of FAP09." (PMID 39021676, 2024). "The APC variant (c.2803_2804insC) was furthermore detected in normal duodenal mucosa adjacent to a tubular adenoma but not in two colonic hyperplastic polyps, again suggesting APC mosaicism restricted to the duodenum." (PMID 40956995, 2025). "Tubular adenomas (TA) derived from FAP patients represent precursor lesions that have an increased likelihood of developing into carcinomas and are normally the result of loss or mutation of the wild-type APC allele." (PMID 34117376, 2021).
hyperplastic polyp (8 papers, 2010 to 2022). A polyp found mainly in the stomach and colon. "Based on the observations that polyps with mutations in the KRAS gene do not develop to cancer and that hyperplastic polyps do not carry a mutation in the APC gene, it seems reasonable to speculate that the first rate-limiting step in the development of CRC are mutations in the APC pathway." (PMID 30029640, 2018).
invasive carcinoma (8 papers, 2010 to 2024). A carcinoma that is not confined to the epithelium, and has spread to the surrounding stroma. "For example, when one copy of the tumor suppressor gene adenomatous polyposis coli (APC) is inherited in humans, LOH leads to polyps in the large intestine that progress to invasive carcinoma." (PMID 27242889, 2016). "Using cBioPortal, here we found that collective % of alteration(s) in WP genes, CTNNB1, APC and DVL1 among breast-invasive-carcinomas was 21% as compared to 56% in PAM50 Basal." (PMID 27281609, 2016).
lymph node metastasis (8 papers, 2001 to 2024). "Mutations in the APC gene were more frequent in primary tumors (71.3%), and a significant difference in prevalence was observed comparing the frequency in lymph node metastases and distant organ metastases (60.9% vs 52.2%)." (PMID 34707195, 2021). "Other factors like FAT3, APC, PTPRD (P = 0.01), lymph-node metastasis, EPHA3, TERT, and STK11 (P = 0.05) that have been found to be related to TMB distribution." (PMID 33996530, 2020). "Among the significant methylated genes, APC, BMP6, BRCA1 and P16 represented higher methylation proportions in matched lymph node metastasis compared to those of the normal tissue (P < 0.05 and P < 0.01, P < 0.0001, P < 0.05; respectively)." (PMID 22695536, 2012). "For lymph node metastasis, ten CpGs from six genes were found to be significant: CDH1 (site 10), CDH13 (sites 7 and 8), MINT3 (sites 3 and 4), CXCL12 (sites 1 and 3), RARB (site 6) and APC (sites 1 and 6)." (PMID 25052224, 2014). "Moreover, APC variation was enriched in the patients without lymph node metastasis." (PMID 38734621, 2024).
metastatic carcinoma (8 papers, 2016 to 2024). A carcinoma which has spread from the original site of growth to another anatomic site. "This suggests a link of APC loss with the oxidative stress in the tumor microenvironment or diet or with the therapies of metastatic cancers." (PMID 37922356, 2023). "In particular, co-mutations of APC with TCF7L2 or SOX9 may identify a subgroup of metastatic cancers with favorable prognosis." (PMID 39587554, 2024). "Patients with APC+/CDKN2A- metastatic cancer survived significantly longer than the patients who are APC-/CDKN2A+ (median survival 52 months compared to 20 months, p < 0.0001)." (PMID 34204917, 2021).
neuroblastoma (8 papers, 2004 to 2024). Neuroblastoma (NB) is the most common solid, extracranial childhood tumor. "It has been reported that APC/C-Cdh1 mediates retinoic acid-induced neuronal differentiation from SH-SY5Y neuroblastoma cells." (PMID 22836916, 2012). "Furthermore, retinoic acid decreases the mRNA and protein levels of Rae1—a nuclear export factor that limits APC/C-Cdh1 activity in mitosis—hence facilitating APC/C-Cdh1-mediated Skp2 degradation, leading to cell cycle arrest and neuroblastoma differentiation." (PMID 22836916, 2012).
Turcot syndrome (8 papers, 2012 to 2025). "Initially, it was recognized that people with Turcot syndrome, a genetic disorder caused by mutations in the adenomatous polyposis coli (APC) gene, a repressor of WNT signaling, had a higher incidence of MB." (PMID 38391759, 2024). "No specific region in the APC gene was identified associated with the occurrence of the Turcot syndrome." (PMID 24148210, 2013). "Current evidence supports the view that both Gardner’s and Turcot syndromes represent phenotypic variants of FAP, rather than distinct clinical entities, all stemming from germline mutations in the APC gene." (PMID 40416288, 2025).
adenomatous colonic polyps (7 papers, 2011 to 2025). "APC mutations were found in 75% of sporadic colonic adenomatous polyps and carcinomas that we examined, while KRAS mutations were found in 25% of cases." (PMID 41488735, 2025). "The first patient with the variant in the APC gene, a female aged 30, had over 1000 adenomatous colonic polyps ranging from 0.2 and 1.0 cm in size, which was an indication for restorative proctocolectomy." (PMID 41170447, 2025). "One form of risk stratification is represented by the ∼tenfold range in colonic adenomatous polyp numbers observed among individuals of FAP families that suggest a range of fetal/juvenile APC mutation rates." (PMID 24195059, 2013). "In humans, APC mutations can be acquired (spontaneous CRC) or inherited as in the autosomal, familiar adenomatous polyposis (FAP), characterized by the formation of multiple colonic adenomatous polyps." (PMID 22168384, 2011).
Alzheimer disease (7 papers, 2016 to 2024). A progressive, neurodegenerative disease characterized by loss of function and death of nerve cells in several areas of the brain leading to loss of cognitive function such as memory and language. "A duplication of the APC Regulator of WNT Signaling Pathway 2 (APC2) gene has been found to be protective against developing Alzheimer disease with psychotic symptoms." (PMID 39367879, 2024).
autism (7 papers, 2012 to 2024). Persistent deficits in social interaction and communication and interaction as well as a markedly restricted repertoire of activity and interest as well as repetitive patterns of behavior. "To elucidate the brain regions that malfunction during autism-like behaviors caused by dysregulation of β-catenin and APC, we used APC conditional knockout (cKO) mice." (PMID 30369876, 2018). "APC cKO mice display autism-like behaviors, consisting of reduced social interest and increased repetitive behaviors, relative to control littermates." (PMID 30369876, 2018). "In a retrospective study in 75 autism spectrum disorder patients and 476 controls an association was found between a SNP in the 3’ untranslated region of the APC gene and autism." (PMID 23083465, 2012). "The deletion of the APC gene was observed in individuals with autism." (PMID 37807632, 2023). "Furthermore, deletions of the APC gene and occurrence of adenomatous polyposis have been reported in patients originally referred for autism." (PMID 32123549, 2020). "The APC/β-cat cKOs buried a comparable number of marbles to control littermates and did not circle, suggesting that lowering β-cat prevents the autism relevant repetitive behavior phenotype seen in APC cKOs." (PMID 32296324, 2020). "Reports have identified cortical pyramidal neurons as an autism-relevant cell type based on convergent expression of ASD genes in both the human and mouse brain, and our APC cKO mouse, using CamKIIα-Cre, predominantly targets forebrain glutamatergic neurons." (PMID 30369876, 2018). "Similar to our finding of reduced SST in the APC cKO mPFC, two other studies suggest that SST interneuron dysfunction may link to autism-like behaviors." (PMID 30369876, 2018).
brain tumors (7 papers, 2009 to 2023). "APC (Adenomatous polyposis coli) was originally identified as a tumour suppressor gene mutated in familial adenomatous polyposis, an autosomal dominant condition with predisposition to colorectal cancers and brain tumours." (PMID 19149881, 2009). "Our laboratory group previously reported on APC exon 11 genetic changes in human brain tumors, brain metastases, and laryngeal squamous cell carcinoma and found 33.3%, 58.8%, and 41% of samples with LOH or mutation of this gene, respectively." (PMID 34064046, 2021). "In addition, four other TSGenes are expressed at two- to eight-fold lower levels in T-ALL compared to brain tumors and/or B-ALL samples: NEDD4L, PLCB3, APC and ZMYND11." (PMID 35401501, 2022).
diabetes (7 papers, 2015 to 2025). "This APC function of insulin-specific B cells is likely their mechanism of action in driving diabetes." (PMID 27834793, 2016). "In fact, overexpressed truncated APC protein not only disrupts or alters β-catenin/Wnt signaling but also affects the rate of β-cell proliferation as well as the total mass of the β-cells, which can contribute to diabetes." (PMID 26110898, 2015). "Although we have not found transcriptional up-regulation of PFKFB3 in the “loser” HPAP datasets, we found that APC/Cdh1 E3 ubiquitin ligase that regulates PFKFB3 stability was down-regulated in T2DHPAP, in line with PFKFB3 protein up-regulation in diabetes." (PMID 39313296, 2024).
parathyroid tumors (7 papers, 2010 to 2022). "Retained parafibromin and APC expression in any parathyroid tumor also argues against malignant potential." (PMID 34421830, 2021). "Promoter hypermethylations of Adenomatous Polyposis Coli (APC) and Ras-association Domain Family Member 1A (RASSF1A) tumor suppressor genes are two common epigenetic changes in parathyroid tumors, which have been interestingly found in the 100% of analyzed PC samples." (PMID 35282432, 2022). "Additional markers such as protein gene product 9.5 (PGP9.5) and adenomatous polyposis coli (APC) could complement parafibromin when assessing malignant potential of parathyroid tumours." (PMID 21197463, 2010). "In parathyroid tumors, the hypermethylation of the tumor-suppressor HIC1, together with RASSF1A, CDKN2B and APC genes, were described in PCas and could be an early event in parathyroid tumor development." (PMID 35586620, 2022).
small intestinal tumors (7 papers, 2016 to 2022). "In the APCMin/+ mice, an inherited APC mutation similar to that in FAP patients causes principally small intestinal tumors, which mimics the residual human disease following colectomy for FAP in regards to both etiology and location." (PMID 33893330, 2021). "The enhancement of invasive properties in small intestinal tumors with a decreased E-cadherin expression was reported in mice with APC and K-Ras mutations." (PMID 27835580, 2016). "Aberrant Wnt/β-catenin and Ras signaling decrease E-cadherin expression, a hallmark of epithelial-mesenchymal transition (EMT), conferring cell motility and invasiveness, and synergistically increases the invasion capacity of small intestinal tumors in mice harboring the APC and K-Ras mutations." (PMID 27835580, 2016). "The occurrence of small intestine tumors was analysed by histology in 18 weeks-old APC+/min mice and age-related WT mice." (PMID 30140377, 2018). "To test the efficacy of targeting integrin αvβ3 to visualize spontaneous genetic model of small intestine tumors, we took advantage of the APC+/min (APC, Adenomatous Polyposis Coli) mouse model." (PMID 30140377, 2018). "An overrepresentation of Bacteroidetes has previously been reported in several studies related to human CRC, as well as in small intestinal tumors in adenomatous polyposis coli (APC) Min/+ mice." (PMID 28959179, 2017).
squamous cell carcinoma (7 papers, 2014 to 2020). A carcinoma arising from squamous epithelial cells. "Whereas the frequencies of RASSF1A and APC methylation were higher in adenocarcinomas, the frequency of p16 methylation was higher in squamous cell carcinomas." (PMID 29570800, 2018). "Three adenocarcinomas, 1 large cell carcinoma, 1 small cell carcinoma, and 1 squamous cell carcinoma harbored gross deletions of APC gene." (PMID 24933634, 2014). "Intense nuclear APC-staining was similar for squamous carcinomas and adenocarcinomas." (PMID 27577083, 2016). "The results showed two hypomethylated genes (CDKN2A and MGMT) and three hypermethylated genes (CDH13, RUNX3, APC) in adenocarcinomas compared with squamous cell carcinomas, with higher sensitivity and specificity values of CDH13 and APC." (PMID 30917582, 2019). "Before chemotherapy, methylation frequencies of APC and/or RASSF1A were 48.9 % (46/94) in adenocarcinoma, 50.0 % (28/56) in squamous carcinoma, and 39.4 % (26/66) in other histological types." (PMID 26550041, 2015).
Wilms tumor (7 papers, 2009 to 2024). An embryonal neoplasm characterized by the presence of epithelial, mesenchymal, and blastema components. "The tumor suppressor APC employs its conserved armadillo repeat (ARM) domain to recognize many of its binding partners, including Amer1/WTX, which is mutated in Wilms' tumor and bone overgrowth syndrome." (PMID 27462415, 2015). "The best known and most studied are Wnt itself (described in Wilms tumors), adenomatous polyposis coli (APC) (responsible for hereditary colon polyposis syndrome), catenin (a protein for cell support and connection with the basal membrane) and T-cell transcription factor (TCF)." (PMID 19597680, 2009). "Both APC and CTNNB1 are classic oncogenes, while AMER1 (also known as the Wilms tumor gene on the X chromosome, WTX) is a tumor suppressor gene." (PMID 31781186, 2019). "Recently in Wilms tumors, WTX (Wilms Tumor gene on the X-Chromosome) was discovered as another component of the β-CATENIN degradation complex where it directly interacts with β-CATENIN and APC." (PMID 20696052, 2010).